ABCA1 (ATP binding cassette subfamily A member 1)
Diseases named in the same sentence as ABCA1 in open-access papers (continued):
Sharing a sentence is not in itself a finding about the gene and the disease.
Cognitive impairment (20 papers, 2012 to 2025). Abnormal cognition is characterized by deficits in thinking, reasoning, or remembering. "ABCA1 has a potential role in the progress of cognitive impairment; a deficiency in ABCA1 reduces the brain APOE but increases the Aβ levels." (PMID 28824418, 2017). "And transgenic animal models have repeatedly shown the influence of loss of ABCA1 on apoE lipidation, Aβ production or deposition and cognitive impairment." (PMID 23181436, 2012). "Treatment with the ABCA1 agonist CS-6253 which reverses the brain pathological effects of apoE4 and the associated cognitive impairments, reverses the effects of apoE4 on the lipidation and aggregation of plasma apoE4 without affecting the total corresponding apoE3 levels." (PMID 27824936, 2016). "Another survey on mouse models confirmed that ABCA1 haplodeficency results in increased Aβ levels and cognitive deficits, but the scale is significantly greater in individuals with the ApoE4 variant." (PMID 41226793, 2025). "Cumulatively, ABCA1-mediated ApoE lipidation is thought to be necessary for the efficient clearance of Aβ and the improvement of cognitive impairment." (PMID 34045954, 2021). "Taken together, these studies show that modulating apoE4 lipidation by increasing ABCA1 expression reduced Aβ accumulation and thereby cognitive deficits." (PMID 33679311, 2021). "Intraperitoneal injection of CS-6253 injection, an ABCA1 agonist peptide, increased apoE4 lipidation, decreased Aβ accumulation and tau hyperphosphorylation as well as reduced cognitive deficits in APOE4-TR mice." (PMID 33679311, 2021). "In conclusion, the present findings show that LXR agonist treatment of Abca1 haplo-deficient APP/E4 mice, ameliorates APOE4 driven brain pathology and cognitive deficits." (PMID 28241068, 2017). "The ATP-binding cassette A1 transporter (ABCA1) gene contributes to both lipid processing and amyloid-β formation and thus shows promise as a biological target in the pathology of mild cognitive impairment (MCI) in T2DM." (PMID 28824418, 2017). "Brain apoE4 is hypolipidated relative to apoE3 and we have recently shown that treatment with the ABCA1 agonist CS-6253 reverses the hypolipidation of apoE4 and concomitantly counteracts the apoE4-driven brain pathology and cognitive impairments." (PMID 27824936, 2016). "Moreover, patients with mild cognitive impairment or AD exhibit a 30% lower ABCA1‐mediated cholesterol efflux capacity compared to cognitively healthy participants." (PMID 39345217, 2024). "Furthermore, Abca1 deficiency increases Aβ deposition as well as CAA in two AD mouse models, and is linked to cognitive deficits in mice." (PMID 35477481, 2022). "We hypothesized that the adverse lipid profiles and the polymorphism of ABCA1, a HDL-c related gene, might be crucial in modulating the pathogenesis of cognitive impairment in diabetic patients." (PMID 28824418, 2017). "ABCA1 219K allele has been suggested to increase the ABCA1 protein function by accelerating cholesterol efflux, altering Aβ secretion, and influencing APOE metabolism, and any of which might be critical in the etiology of cognitive impairment." (PMID 28824418, 2017). "Selective stimulation of Abca1 with an ABCA1 agonist in mice expressing human APOE ε4, increased lipidation of ApoE ε4 and ameliorated ApoE ε4-driven cognitive impairments and brain pathology, rendering it to a similar level as the mice expressing ApoE ε3." (PMID 35477481, 2022). "In humans, we and others have demonstrated that the CSF from mild cognitive impairment (MCI), and AD, patients showed a lower ability to induce ABCA1- and ABCG1-efflux." (PMID 33287338, 2020). "In APP transgenic mice, lack of Abca1 increased Aβ deposition and cognitive deficits." (PMID 28241068, 2017).
Cognitive impairment (continued). "However, intra-hippocampal infusion of scrambled A oligomers affected cognitive performance of Abca1 KO mice, which also showed altered neurite architecture in the hippocampus, suggesting that mice lacking ABCA1 have basal cognitive deficits that prevent them from coping with additional stressors." (PMID 33562440, 2021).
glaucoma (20 papers, 2016 to 2025). Increased pressure in the eyeball due to obstruction of the outflow of aqueous humor. "ABCA1 is expressed in the retina, including RGCs, and its reduced expression is considered a risk factor for glaucoma." (PMID 40079201, 2025). "Previous studies have indicated that reduced ABCA1 expression is associated with increased susceptibility to neurodegenerative diseases, including glaucoma." (PMID 40079201, 2025). "Our meta-analysis conducted a detailed evaluation across several genetic models to assess the relationship between ABCA1 polymorphism and glaucoma risk." (PMID 39612451, 2024). "In conclusion, the relationship between ABCA1 polymorphism and glaucoma risk appears to be modulated by ethnic background, with a significant association observed in the Asian population but not in Caucasian or mixed groups." (PMID 39612451, 2024). "Over the past decade, the advent of genome-wide association studies (GWAS) and insights from mouse models have shed light on the genetic underpinnings of glaucoma, with particular emphasis on the association between the ABCA1 gene and the disease." (PMID 39612451, 2024). "By aggregating data from a wide array of studies, this meta-analysis seeks to provide a more definitive stance on the connection between ABCA1 gene variations and the risk of developing glaucoma, particularly in diverse populations worldwide." (PMID 39612451, 2024). "ABCA1 deficiency in the retinal astrocytes induced glaucoma-like optic neuropathy in aged mice and resulted in RGC degeneration." (PMID 38275823, 2024). "This inconsistency across various studies necessitates a comprehensive examination of the available evidence to discern the potential genetic association between ABCA1 polymorphisms and glaucoma risk." (PMID 39612451, 2024). "Our meta-analysis elucidates that the association between ABCA1 polymorphism and glaucoma susceptibility varies significantly across different ethnic groups." (PMID 39612451, 2024). "Odds ratios (ORs) with 95% confidence intervals (CIs) were calculated to quantify the strength of the association between ABCA1 polymorphisms and glaucoma risk." (PMID 39612451, 2024). "In particular, SNPs within the gene responsible for encoding ATP-binding cassette transporter A1 (ABCA1), a membrane transporter involved in phospholipids and cholesterol, have been reported to be linked with human glaucoma." (PMID 38275823, 2024). "Genome-wide association studies (GWAS) found that common variants near the ATP-binding cassette (ABC) transporter A1 (ABCA1) gene are associated with glaucoma." (PMID 38983051, 2023). "Although the association of AFAP1 and ABCA1 genes with cancer has been widely studied, there is a paucity of data showing the underlying mechanism in glaucoma." (PMID 35741817, 2022). "Previously, SNP rs2472493 in ABCA1 was associated with POAG in the genome-wide meta-analysis of 18 population cohorts from the International Glaucoma Genetics Consortium." (PMID 35719397, 2022). "Other risk factors for glaucoma include age, family history of glaucoma, diabetes mellitus, and genes related to lipid metabolism, such as ABCA1 and ELOVL5." (PMID 36012964, 2022). "Several genome-wide association studies found that common variants near the ATP-binding cassette (ABC) transporter A1 (ABCA1) gene are associated with glaucoma." (PMID 30364320, 2018). "Variants near the ATP-binding cassette transporter A1 (ABCA1) gene are associated with elevated intraocular pressure and newly discovered risk factors for glaucoma." (PMID 30364320, 2018). "This meta-analysis aims to comprehensively assess whether genetic variations in ABCA1 significantly contribute to the susceptibility to glaucoma." (PMID 39612451, 2024). "Our findings indicate that ABCA1 polymorphisms may play a role in increasing the risk of glaucoma, specifically within Asian populations." (PMID 39612451, 2024). "GWAS show that an ABCA1 polymorphism predisposes individuals to glaucoma." (PMID 29682502, 2018).
glaucoma (continued). "Therefore, the current study aims to consolidate and analyze the disparate findings through a systematic meta-analysis, endeavoring to clarify the role of ABCA1 polymorphisms in glaucoma susceptibility and contribute to the broader understanding of its genetic etiology." (PMID 39612451, 2024). "Understanding the physiological and pathological involvement of ABCA1 in glaucoma and the potential benefits of targeting ABCA1 for the treatment of glaucoma still require more research." (PMID 39049847, 2024). "Based on these findings, enhancing the ABCA1 signaling pathway is proposed as a potential therapeutic approach for glaucoma and ocular hypertension treatment." (PMID 38562304, 2024). "Polymorphisms rs2472493 near ABCA1, rs7636836 in FNDC3B, and rs61275591 near the ANKRD55–MAP3K1 genes were previously reported to exhibit genome-wide significance in primary open-angle glaucoma (POAG)." (PMID 36980976, 2023). "Recently, the implication of glial cholesterol metabolism, especially via ABCA1, in glaucoma, has been elegantly demonstrated." (PMID 38983043, 2023). "A recent study provided another evidence for the possible role of dysregulation of cholesterol homeostasis in glaucoma via the characterization of Abca1 KO mice." (PMID 38983043, 2023). "Association of rs2472493 (ABCA1) and rs7636836 (FNDC3B) polymorphisms with the risk of primary angle-closure glaucoma compared to control under different genetic models." (PMID 35719397, 2022). "Minor allele frequency of rs2472493 in ABCA1 and rs7636836 in FNDC3B genes according to glaucoma types and gender." (PMID 35719397, 2022). "Three genetic loci (AFAP1, BICC1, and ABCA1) were identified in four or more approaches in our pipeline, confirming earlier evidence that these genes have a likely role in glaucoma pathogenesis." (PMID 35741817, 2022). "Several lines of evidence including GWAS, animal models and in vitro studies suggest ABCA1 plays an important role in the pathophysiology of glaucoma, mainly POAG." (PMID 33562440, 2021). "At present, there are few studies on the function and mechanism of ABCA1 in glaucoma." (PMID 39049847, 2024). "Abca1 has been the most studied gene of cholesterol metabolism in the context of glaucoma." (PMID 38983043, 2023). "Expression of ABCA1 has been confirmed in several ocular tissues relevant to glaucoma." (PMID 36980976, 2023). "In another glaucoma model, ABCA1 was related to RGC apoptosis." (PMID 36980976, 2023). "There are enough data to implicate the role of ABCA1 in eye diseases, including glaucoma." (PMID 36980976, 2023). "Accordingly, we investigated the genetic association of two previously reported primary open-angle glaucoma (POAG)-related gene polymorphisms, rs2472493 (A > G) in ABCA1 and rs7636836 (C > T) in FNDC3B, in primary angle-closure glaucoma (PACG) and pseudoexfoliation glaucoma (PXG)." (PMID 35719397, 2022). "ABCA1 is expressed in all the major tissues of the eye, including the trabecular meshwork, Schlemm’s canal endothelial cells, RGCs, and optic nerve that are primarily involved in glaucoma." (PMID 35719397, 2022). "Given the overlapping clinical manifestations and common genetic variants reported among glaucoma types, we investigated the association of two POAG-related gene polymorphisms, rs2472493 in ABCA1 gene and rs7636836 near FNDC3B, in the PACG and PXG patient cohort of Saudi origin." (PMID 35719397, 2022). "Based on their findings, the authors suggest that enhancing the ABCA1 signaling pathway could be of therapeutic value in the treatment of glaucoma and ocular hypertension." (PMID 33562440, 2021). "Our findings identify a novel mechanism for ABCA1 in glaucoma." (PMID 30364320, 2018). "Susceptibility to Alzheimer's disease is associated with ABCA1, APOE4, GST, and CYP46A1 polymorphisms, which may share mechanistic steps with glaucoma." (PMID 29682502, 2018). "However, the exact mechanism(s) by which ABCA1 may be involved in glaucoma pathogenesis is still unclear." (PMID 35719397, 2022).
glaucoma (continued). "Additionally, they confirmed that ABCA1 had higher expression in the trabecular meshwork of POAG patients versus controls, confirming previous work suggesting the enhanced expression of ABCA1 as a diagnostic marker for glaucoma." (PMID 34440309, 2021). "However, the function of ABCA1 in animal models of glaucoma is still unclear." (PMID 30364320, 2018). "However, in mouse models of glaucoma, it is still unclear whether ABCA1 participates in ANXA1 membrane translocation, and whether and how blocking TBK1 directly protects against RGC apoptosis." (PMID 30364320, 2018). "The evidence suggests the pathogenesis of glaucoma, particularly in POAG, is significantly influenced by ABCA1." (PMID 39049847, 2024). "Regarding the genetic aspect, SNPs with high OR values for glaucoma exposure on cataract were TMCO1-AS1 (rs2814471 with OR = 1.370), GAS7 (rs12602519 with OR = 1.178), ABCA1;SLC44A1 (rs2472493 with OR = 1.162), and GNB1L;TXNRD2 (rs58714937 with OR = 1.153)." (PMID 38674349, 2024). "ABCA1, FNDC3B, and ANKRD55–MAP3K1 are all highly expressed in the tissues relevant to glaucoma, supporting their plausible role in ocular development and glaucoma-related phenotypes." (PMID 36980976, 2023). "ABCA1 is highly expressed in retinal ganglion cells and its expression is significantly higher in individuals with glaucoma and upregulated in high-IOP glaucoma murine models." (PMID 33562440, 2021).
melanoma (20 papers, 2009 to 2025). A malignant, usually aggressive tumor composed of atypical, neoplastic melanocytes. "Altogether, the results suggest that high expression of ABCA1 is linked with highly aggressive clinical behavior of human melanoma." (PMID 37312227, 2023). "Many studies have revealed that ABCA1 is associated with a malignant phenotype in various carcinomas, including breast, colon, and lung cancers and melanoma." (PMID 36672209, 2023). "An immunohistochemical study on the ABCA1 level in 110 patients-derived melanoma tumors was performed to investigate the potential association of the transporter with melanoma stage of progression and prognosis." (PMID 37312227, 2023). "In the present study, we show that myeloid loss of Abca1 alone was sufficient to confer enhanced tumor immunity in both melanoma and bladder cancer." (PMID 29069761, 2017). "Moreover, reduced immunoreactivity of ABCA1 in melanoma cells was significantly associated with low risk of recurrence (p = 0.003)." (PMID 37312227, 2023). "The mRNAsi results showed that elevated intracellular cholesterol was positively associated with melanoma stemness, through activation of DHCR24 in cholesterol biosynthesis or inhibition of efflux by ABCA1, and ABCG1." (PMID 38775844, 2024). "Double knockdown of ALKBH5 and ABCA1 attenuated the inhibition by singly silencing ALKBH5 of melanoma tumor growth in mice reflected by the increase of tumor size and tumor weight." (PMID 38481816, 2024). "The real-time PCR analysis showed a significant (over 12-fold) increase in ABCA1 expression in both resistant melanoma cell lines compared to control cells." (PMID 39175042, 2024). "To further understand the impact of ABCA1 activity on human melanoma progression, we analyzed the protein level of ABCA1 in five different melanoma cell lines using the Western blot technique." (PMID 37312227, 2023). "We demonstrate that the loss of ABCA1 activity alters motility, invasion, and extracellular matrix (ECM) degradation processes of melanoma cells." (PMID 37312227, 2023). "Overexpression of ABCA1 in melanoma cells significantly correlated with shorter cancer-specific overall survival and shorter disease-free survival (p = 0.007 and p < 0.001, respectively)." (PMID 37312227, 2023). "All these outcomes suggest that the ABCA1 activity is involved in the motility of melanoma cells, impacting their signalization, migration and invasion abilities but not proliferation in vitro." (PMID 37312227, 2023). "To investigate the impact of ABCA1 on human melanoma progression and level of aggressiveness, we first performed an immunohistochemical study on the ABCA1 level in 110 patients-derived melanoma tumors." (PMID 37312227, 2023). "In conclusion, we show, to our utmost knowledge, for the first time a clinical correlation between human melanoma progression and ABCA1 expression." (PMID 37312227, 2023). "Our first observation that high ABCA1 expression level in clinical samples correlates with more advanced tumors indicates an important role of ABCA1 in melanoma progression." (PMID 37312227, 2023). "As we observed that ABCA1 activity altered Hs294T spontaneous migration, we investigated more precisely how ABCA1 influenced the motility of melanoma cells." (PMID 37312227, 2023). "Human melanoma cells reorganize their plasma membrane cholesterol content and organization via ABCA1 activity to promote motility processes and aggressiveness potential." (PMID 37312227, 2023). "In particular, ABCA1 upregulation exacerbates the progression of colorectal cancer, melanoma, and bladder cancer; ABCA1 expression is also significantly elevated in triple-negative breast cancer tissue than in normal breast tissue." (PMID 37874419, 2023). "This possibility is further supported through a study that showed deletion of ABCA1 in myeloid cells prevented melanoma tumour growth in synergetic C57/B6 mice." (PMID 35408842, 2022).